MSMO1 (methylsterol monooxygenase 1)
Description:
Catalyzes the three-step monooxygenation required for the demethylation of 4,4-dimethyl and 4alpha-methylsterols, which can be subsequently metabolized to cholesterol. Also involved in drug metabolism, as it can metabolize eldecalcitol (ED-71 or 1alpha,25-dihydroxy-2beta-(3-hydroxypropoxy)- cholecalciferol), a second-generation vitamin D analog, into 1alpha,2beta,25-trihydroxy vitamin D3; this reaction occurs via enzymatic hydroxylation and spontaneous O-dehydroxypropylation.
Synonyms: DESP4; ERG25; SC4MOL; MCCPD
Tractability: Antibody: its Gene Ontology location is reachable by antibodies, with high confidence; UniProt predicts a signal peptide or a membrane-spanning region. PROTAC: UniProt records ubiquitination sites on it; ubiquitination databases record sites on it; its protein half-life has been measured.
Target class: Enzyme; Oxidoreductase
Gene: Protein-coding gene on chromosome 4 (165,327,667 to 165,343,180, forward strand). Ensembl gene ENSG00000052802.
Subcellular location: Endoplasmic reticulum membrane
Subcellular location (Human Protein Atlas): Endoplasmic reticulum
Pathways (Reactome):
Metabolism: Cholesterol biosynthesis via desmosterol (Bloch pathway); Zymostenol biosynthesis via lathosterol (Kandutsch-Russell pathway)
Gene Ontology:
Molecular function: C-4 methylsterol oxidase activity; protein binding; iron ion binding
Biological process: cholesterol biosynthetic process; fatty acid metabolic process; steroid metabolic process; zymosterol biosynthetic process; lipid biosynthetic process
Cellular component: endoplasmic reticulum; endoplasmic reticulum membrane; membrane; plasma membrane
Genetic constraint (gnomAD): Loss-of-function variants: 16 observed, 26.98 expected, observed/expected ratio (o/e) 0.59, 90% interval 0.4 to 0.9. The synonymous counts are far from expectation, so gnomAD's model fits this gene poorly and the ratio says little. Missense variants: 242 observed, 303.31 expected, observed/expected ratio (o/e) 0.8, 90% interval 0.72 to 0.89. Synonymous variants: 71 observed, 97.88 expected, observed/expected ratio (o/e) 0.73, 90% interval 0.6 to 0.88.
Homologues: Orthologues: chimpanzee MSMO1 (100% identical), macaque MSMO1 (99% identical), dog MSMO1 (96% identical), pig MSMO1 (96% identical), dog MSMO1 (93% identical), rabbit MSMO1 (92% identical), guinea pig MSMO1 (92% identical), mouse Msmo1 (89% identical), rat Msmo1 (89% identical), zebrafish msmo1 (79% identical), tropical clawed frog msmo1 (78% identical). Paralogues in human: FAXDC2 (26% identical), CH25H (25% identical), SC5D (23% identical).